ATP7B (ATPase copper transporting beta)
Diseases named in the same sentence as ATP7B in open-access papers (continued):
Sharing a sentence is not in itself a finding about the gene and the disease.
Wilson disease (continued). "However, targeting ATP7B to reduce Pt tolerance in tumors could represent a serious risk because suppression of ATP7B might compromise copper homeostasis, as happens in Wilson disease." (PMID 32155756, 2020). "Wilson disease (WD) is genetically induced failure of copper metabolism caused by mutations in the ATP7B gene located on chromosome 13 and is inherited in an autosomal, recessive pattern." (PMID 31718567, 2019). "Wilson disease (WD) is an autosomal recessive disorder of impaired copper metabolism caused by mutations in the ATP7B gene, which encodes a copper-transporting ATPase involved in copper transportation across cell membranes." (PMID 31277686, 2019). "Wilson Disease (WD) is a hereditary genetic disorder, which coincides with a dysfunctional copper (Cu) metabolism caused by mutations in ATP7B, a membrane-bound P1B-type ATPase responsible for Cu export from hepatic cells." (PMID 29063292, 2017). "Deficiency of one of the copper transporters ATP7A and ATP7B leads to the rare X-linked disorder Menkes Disease (MD) or the rare autosomal disorder Wilson disease (WD), respectively." (PMID 27587995, 2016). "Wilson’s disease is an autosomal recessive inherited disease, characterised by excessive copper storage in the body, especially the liver and brain, and also in the heart tissue due to reduced biliary copper excretion secondary to loss of the mutation for copper-transporting ATPase (ATP7B)." (PMID 27176875, 2016). "Similarly, mutations in ATP7B (Wilson’s disease) affect biliary copper excretion, resulting in hepatic copper accumulation, which may trigger liver failure if not treated." (PMID 27472369, 2016). "Wilson disease (WD) is a rare autosomal recessive disorder, which leads to copper metabolism, due to mutations in ATP7B gene." (PMID 24734161, 2014). "Mutations in the copper (Cu) transporter gene ATP7B, the primary cause of Wilson disease (WD), result in high liver Cu and death of hepatocytes." (PMID 24892424, 2014). "Wilson disease (WD) is an autosomal recessive inherited disorder of copper metabolism caused by mutations of the hepatic copper transporting ATPase ATP7B, which facilitates biliary copper excretion." (PMID 21595966, 2011). "Wilson disease (WD) is an autosomal recessive disease that is caused by a loss-of-function mutation in the ATP7B gene and is characterized by hypoceruloplasminemia and excessive accumulation of copper in various organs." (PMID 21676234, 2011). "Wilson disease (WD) results from accumulation of copper and caused due to mutations in ATP7B, a copper transporting ATPase." (PMID 20550661, 2010). "BACKGROUND: Genetic studies have reported the ATP7B c.3316 G > A variant in Wilson disease (WD)." (PMID 41691313, 2026). "Wilson disease (WD) is a multisystem disorder in which copper accumulates in various tissues, exceeding the carrying capacity of ceruloplasmin and causing tissue damage, as a result of mutations in the ATP7B gene found in many tissues." (PMID 41250701, 2025). "P/LP variants were identified in MUTYH (14 individuals) and ATP7B (5 individuals), known to cause MUTYH‐Associated Polyposis and Wilson disease respectively when present in the compound heterozygous or homozygous state." (PMID 40970488, 2025). "These variants were most frequent in HFE (n = 207, 5.21%), MUTYH (n = 91, 2.29%) and ATP7B (n = 73, 1.84%), associated with hereditary haemochromatosis, MUTYH-associated polyposis (MAP), and Wilson disease." (PMID 40332002, 2025). "It is primarily associated with a recessive mutation in the COMMD1 gene, also known as MURR1, an interacting ATP7B protein, which impairs hepatic copper excretion and leads to copper accumulation in the liver as observed in Wilson disease." (PMID 41480142, 2025). "Four confirmed Wilson Disease cases at site 3 (cases 2, 6, 7, and 11) had ATP7B 887 levels above the initial range cutoff, while the ATP7B 1056 levels were below the cutoff." (PMID 39846592, 2025).
Wilson disease (continued). "Wilson’s disease (WD; OMIM 277900) is an autosomal recessive disorder caused by pathologic variants in the copper (Cu)-transporting ATPase beta (ATP7B) gene." (PMID 40104154, 2025). "The BS1 values in this study ranged from 0.000003 for WT1-related Wilms tumor to 0.0058 for ATP7B-related Wilson disease." (PMID 41000626, 2025). "The clinical manifestations of Wilson disease (WD) are related to copper accumulation in the liver and brain, but little is known about the role of other organs expressing the ATP7B copper transporter on metabolic and ultrastructural changes characterizing WD." (PMID 41109666, 2025). "Two Wilson Disease patients (site 2 case 1 and site 3 case 10) had ATP7B 1056 levels above the cutoff, but ATP7B 887 levels were below the cutoff." (PMID 39846592, 2025). "The highest CrF after averaging across eight genetic ancestries was for BTD (AR; biotinidase deficiency; 1/17; 382 million), followed by HFE (AR; hemochromatosis; 1/28; 471 million) and ATP7B (AR; Wilson disease; 1/54; 137 million)." (PMID 40162233, 2025). "Inactivation of Atp7b in the mouse intestine alters the processing of dietary fat and modifies liver metabolome, thus contributing to Wilson’s disease pathogenesis." (PMID 39172219, 2025). "Gene replacement therapy theoretically can lead to potential cure of genetic disorders through delivering a functional ATP7B gene (cDNA) into Wilson disease patients, but major hurdles for its application calls for caution." (PMID 38731973, 2024). "The gold standard for the diagnosis of Wilson disease is ATP7B gene testing, but it is often abandoned because of limited economic conditions." (PMID 39432607, 2024). "The first AR metabolism disease detected is Wilson’s disease, a disorder of copper metabolism coded by the ATP7B gene." (PMID 38553482, 2024). "Relevant genetic information: Genetic analysis revealed that John carried 2 mutations in the ATPase copper transporting beta (ATP7B) gene, confirming the diagnosis of Wilson Disease." (PMID 38306527, 2024). "Lentiviral gene transfer that integrates the ATP7B gene into the genome has been shown to be effective for ameliorating disease progression in animal models of Wilson disease." (PMID 38731973, 2024). "In cases of ATP7B dysfunction, such as Wilson’s disease, copper accumulates in the liver, leading to liver damage and subsequent health issues." (PMID 38218941, 2024). "It is well documented that ATP7B is intertwined with lipid metabolism and can damage crucial cellular organelles for ROS energy metabolism during the development of Wilson’s disease." (PMID 38690269, 2024). "Consistently, these findings were validated in a mouse model of Wilson's disease mouse model with Atp7b depletion (Atp7b−/−)." (PMID 39430913, 2024). "Previous studies have predominantly concentrated ATP7B’s function in copper metabolism disorders or elevated resistance to platinum-based chemotherapy such as Wilson’s disease and, its involvement in Alzheimer’s disease and cancer." (PMID 38690269, 2024). "We report a case of Wilson disease (WD) with dilated cardiomyopathy in which whole-genome sequencing (WGS) revealed the rare co-occurrence of two novel compound heterozygous ATP7B pathogenic variants (NM_001005918.3:c.2250del/p.N751Tfs*9 and c.3496C>T/p.L1166F) and a known FLNC pathogenic variant." (PMID 39209822, 2024). "The GPP rate was especially high for the MUTYH and ATP7B genes, which indicate a high carrier rate of MUTYH-Associated Polyposis and Wilson disease in the Qatari population." (PMID 39020067, 2024). "In a 2022 paper from China, researchers provided clinical and genetic characterization of variations of the ATP7B gene in subjects with Wilson’s disease." (PMID 38928192, 2024). "We noted that Wilson's disease (WD), which is characterised by a copper metabolic disturbance due to inheritable malfunctioning or missing Atp7b protein, can also lead to psychiatric symptoms." (PMID 39581695, 2024).
Wilson disease (continued). "One consideration is that Wilson disease is a systemic disease with ATP7B expression in multiple cell types." (PMID 38731973, 2024). "Wilson disease (WD) is a rare copper metabolism disorder caused by mutations in the ATP7B gene." (PMID 37510937, 2023). "The LPP rat is a Wilson animal model with genetic ablation of ATP7B and growing rats develop different stages of Wilson’s disease (classified as affected, disease onset, and diseased) over time." (PMID 37311819, 2023). "Remarkably, these in vitro findings were further validated in a Wilson’s disease mouse model with Atp7b depletion (Atp7b−/−)." (PMID 36755067, 2023). "After extensive sequencing analysis, three different partial intragenic deletions were identified in ATP7B in seven different unexplained autosomal recessive Wilson disease (WD; OMIM: #277900) families using selective amplification and MLPA." (PMID 36672937, 2023). "In this couple, the woman was first screened as an extensibility carrier for 15 genetic diseases, and the results showed that she was a carrier of the pathogenic genes ATP7B and GJB2 for Wilson’s disease and hereditary deafness, respectively." (PMID 37031186, 2023). "Wilson disease (WD) is an autosomal recessive inherited disorder of copper metabolism disorder caused by mutations in ATP7B, which encodes a copper-transporting P-type ATPase (ATP7B)." (PMID 38020085, 2023). "Two homologous Cu transporters, Atp7a (Menkes disease protein) and Atp7b (Wilson disease protein), maintain Cu homeostasis in the tissue." (PMID 36626371, 2023). "Two ATP7B variants were detected using genotype-driven analysis in WGS, and subsequent serum copper and ceruloplasmin tests confirmed the diagnosis of Wilson’s disease." (PMID 37180992, 2023). "Today, we know that Wilson disease (WD) is due to an impairment of the mostly liver-residing copper-transporting ATPase ATP7B." (PMID 34857647, 2022). "To better understand the role of ATP7B in hepatocytes and to provide a smart tool for the development of novel therapies against Wilson disease, we used the CrispR/Cas9 tool to generate hepatocyte cell lines with the abolished expression of ATP7B." (PMID 36359796, 2022). "Excessive accumulation of copper in ATP7B mutant cells leads to pathology progression such as insoluble Mallory body (MB) in Wilson disease (WD)." (PMID 35349929, 2022). "Wilson disease (WD) is a rare autosomal recessive disorder caused by a mutation in the ATP7B gene." (PMID 36004917, 2022). "Homozygous or compound heterozygous mutations in the ATP7B gene caused Wilson disease (WD), characterized by excessive copper accumulation in various organs, such as the brain, liver, and cornea, leading to a wide spectrum of symptoms from hepatic to neuro-psychiatric." (PMID 36553628, 2022). "Wilson disease (WD, OMIM entry: 277 900) is a rare autosomal recessive genetic disorder associated with various mutations in the ATP7B gene." (PMID 35357466, 2022). "Method validation is performed by measuring serum collected from either control (Atp7b+/+) or Wilsons disease rats (Atp7b−/−)." (PMID 35682788, 2022). "ATP7B-related Wilson disease and KMT2D-related Kabuki syndrome were observed in 3 (7.0%) and 2 (4.7%) patients, respectively." (PMID 34539730, 2021). "In this study, we tested the efficacy of bc-TTM in reducing hepatic Cu content in Atp7b−/− mice, representing a well-established experimental Wilson’s disease model." (PMID 34944677, 2021). "It is worth to mention, that UGT1A1 protein abundance is decreased in Atp7b−/− mouse model of Wilson’s disease." (PMID 34117631, 2021). "Mutations of the ATP7B gene (OMIM, 606882) cause Wilson disease (OMIM, 277900), which is an inherited disorder of copper accumulation in various tissues resulting in hepatic and neurological manifestation." (PMID 34831341, 2021).
Wilson disease (continued). "Wilson's disease (WD, OMIM:277900) is an autosomal recessive disorder of copper metabolism caused by ATP7B gene (OMIM:606882) pathogenic mutations, which can lead to multiple organ and multisystem damage and seriously affect the quality of life of patients." (PMID 34240825, 2021). "Dysfunctional ATP7B, a copper-transporting ATPase, is involved in the development of monogenic Wilson disease, a disorder characterized by disturbed copper transport." (PMID 34831341, 2021). "Wilson’s disease and Menkes disease are neurodevelopmental disorders resulting from mutations in the copper transporters ATP7A and ATP7B, with ATP7A mutations also causing occipital horn syndrome, and distal motor neuropathy." (PMID 33359139, 2021). "The effects of copper overload can be easily analyzed in Wilson’s disease (WD), a genetically determined condition inherited in an autosomal recessive (OMIM # 277900) resulting from pathogenic mutations in the ATP7B gene encoding ATP-ase7B." (PMID 33291628, 2020). "Wilson disease, in which a Cu “pump” (ATP7B) in hepatocytes is dysfunctional, results in accumulations of large amounts of Cu in the liver that eventually lead to hepatic Cu overload as well as excess accumulation in some other tissues, such as the brain." (PMID 32668621, 2020). "Inconsistent with this finding, a transcriptome analysis of the liver in the mouse model of Wilson’s disease under copper-transporting, P-type ATPase gene Atp7b knockout identified the PPAR signaling pathway as a high-copper-responsive target pathway." (PMID 32485807, 2020). "Clinical signs, biochemical parameters, histologic findings, and/or ATP7B genetic testing are required to diagnose Wilson's disease." (PMID 32774387, 2020). "Wilson’s disease (WD) is an autosomal recessive disorder of ATP7B gene leading to impaired copper metabolism." (PMID 32270360, 2020). "In animals with Wilson disease (Atp7b mutants), indeed very high accumulation of copper was observed in the organ and accordingly liver was injured." (PMID 32010131, 2019). "Wilson disease (WD) is an autosomal recessive disease caused by copper accumulation mainly in the liver and in the brain as a result of mutations affecting the copper transporter gene, ATPase copper transporting beta (ATP7B)." (PMID 30709419, 2019). "This difference is underscored by the two genetic disorders, Menkes and Wilson diseases, which are caused by mutations in ATP7A and ATP7B, respectively, and lead to very different clinical manifestations." (PMID 31540259, 2019). "Tetrathiomolybdate (TM) is used in the clinic for the treatment of Wilson’s disease by targeting the cellular copper efflux protein ATP7B (WLN)." (PMID 30643139, 2019). "To improve the sensitivity and reproducibility of the assay, we harnessed the immuno-SRM platform to quantify very low abundance peptides in DBS such as surrogate peptides of the ATP7B protein from patients with Wilson disease (WD)." (PMID 30564228, 2018). "Copper metabolism imbalance in Atp7b-/- knockout mouse model of Wilson’s disease was assessed with PET/CT using radioactive copper-64 chloride (64CuCl2) as a tracer." (PMID 29392086, 2018). "In this study, we identified mutations in the ATP7B gene of three patients’ families with Wilson disease by sequencing the entire coding region and adjacent splice sites of the ATP7B gene." (PMID 29914392, 2018). "Background and Objective: In Wilson’s disease, copper metabolism is impaired due to defective copper transporting protein ATP7B, resulting in copper accumulation in liver and brain and causing damage to liver and brain tissues." (PMID 30344245, 2018). "On the other hand, ATP7B is mostly responsible for Cu efflux from hepatocytes and impairment of ATP7B function due to mutations results in an autosomal recessive disorder known as Wilson disease (WD)." (PMID 29063292, 2017).
Wilson disease (continued). "In the human cytoplasm, after the uptake of Cu ions, the Cu chaperone Atox1 transports the metal to the membrane-bound ATP7A and ATP7B (Menke’s and Wilson disease proteins, respectively), two homologous P1B-type ATPases located in the trans-Golgi network." (PMID 27744583, 2017). "According to our knowledge based on PubMed data this is the first report on next-generation sequencing of the ATP7B gene for genetic diagnosis of Wilson's disease in a clinical setting." (PMID 26819605, 2016). "Two well documented copper metabolism disorders in humans are Menkes disease and Wilson disease which are induced by mutations of genes coding for the copper transport proteins, ATP7A and ATP7B, respectively." (PMID 26861285, 2016). "Furthermore, based on the observations in the Labrador retrievers, mutations in ATP7A, with a subtle effect, may be involved as modifiers in Wilson disease and may explain part of the observed difference in ATP7B mutation frequency and presence of clinical disease." (PMID 26861285, 2016). "It is noteworthy that ApoJ also interacts with the ATP7A and ATP7B copper transporters that are defective in Menkes and Wilson diseases, respectively." (PMID 23720634, 2013). "We present here a multidisciplinary approach using molecular modeling tools and surface plasmonic resonance to study the function of the ATP7B protein, which is impaired in the Wilson disease." (PMID 22046264, 2011). "Studies on the Wilson disease protein showed that COMMD1 participates in the ATP7B-mediated copper-excretion pathway." (PMID 21483833, 2011). "ATP7B is involved in biliary secretion of copper, and its malfunction is responsible for Wilson disease." (PMID 22216111, 2011). "They found that the Wilson's disease ATP7B gene—which is a tight control balance regulator for free copper levels in the body—presents susceptibility loci for late-onset Alzheimer's disease." (PMID 21949909, 2011). "Other, less frequent variants were related to HNF1A-maturity onset of diabetes of the young, MODY, (n = 7, 0.18%); HFE-related haemochromatosis (n = 2, 0.05%); ACVRL1-hereditary haemorrhagic telangiectasia (n = 2, 0.05%); and ATP7B–Wilson disease (n = 1, 0.03%)." (PMID 40332002, 2025). "Four additional cases (#6, 7, 20, 31) were heterozygous for known likely pathogenic or pathogenic variants, with no second pathogenic variants in the ATP7B gene, indicating these samples are most likely carriers for Wilson Disease." (PMID 39846592, 2025). "Defective ATP7B function leads to copper metabolism dysfunction and excessive copper accumulation, particularly in the liver and brain, resulting in the hepatic and neurological features of Wilson’s disease." (PMID 40616145, 2025). "Moreover, this study showed that the frequency of the ATP7B gene (Wilson disease) was high, accounting for 2.54% (or 1 in 40)." (PMID 40447697, 2025). "The ATP7B gene is also associated with SFN, and demyelinating polyneuropathy may occur with moderate Wilson’s disease symptoms." (PMID 39000354, 2024). "A copper-insensitive Wilson disease-causing pathogenic variant, ATP7B-S653Y, did not exit the TGN in wild-type MDCK cells, but trafficked to the apical plasma membrane in a copper-independent manner in pan-AP-1 KO MDCK cells." (PMID 38032054, 2024). "In this present study, we have utilized multiple Wilson disease-causing pathogenic variants as well as the ΔF37–E45 deletion to characterize possible associated changes at the N-terminus that influence TGN exit and subsequent trafficking of ATP7B." (PMID 38032054, 2024). "For example, Wilson’s Disease (WD) is a classic example of excess copper levels, manifested in the liver by the inactivation of the copper transporter ATP7B and the continuous accumulation of copper, resulting in DNA damage, lipid peroxidation, and mitochondrial dysfunction." (PMID 38200525, 2024).